SNORD83A (small nucleolar RNA, C/D box 83A)
Synonyms: U83A; RNU83A
Gene: Small nucleolar RNA gene on chromosome 22 (39,315,213 to 39,315,307, reverse strand). Ensembl gene ENSG00000209482.
Gene Ontology:
Biological process: RNA processing
Cellular component: nucleolus
Homologues: Orthologues: chimpanzee SNORD83A (100% identical), macaque SNORD83A (94% identical), rabbit SNORD83A (81% identical), pig SNORD83A (80% identical), guinea pig SNORD83A (74% identical), mouse Gm55357 (59% identical), zebrafish SNORD83A (58% identical). Paralogues in human: SNORD83B (79% identical).
Diseases named in the same sentence as SNORD83A in open-access papers:
SNORD83A is named in the same sentence as 1 disease in open-access papers, as found by Europe PMC text mining. Sharing a sentence is not in itself a finding about the gene and the disease.
SNORD83A shares sentences with these, for which no sentence is quoted: HIV-1 infection (1 paper).